CCR6 (C-C motif chemokine receptor 6)
Diseases named in the same sentence as CCR6 in open-access papers (continued):
Sharing a sentence is not in itself a finding about the gene and the disease.
sarcoidosis (9 papers, 2017 to 2025). Sarcoidosis is a multisystemic disorder of unknown cause characterized by the formation of immune granulomas in involved organs. "The behaviour of Th17 cells in peripheral blood can be complex, as some studies indicate that memory CCR6+ T cells are more abundant in sarcoidosis groups, whereas in some studies IL-17A-producing cells numbers are low in peripheral blood." (PMID 41376646, 2025). "Th1 and Th17.1 cells in sarcoidosis-affected skin induced NF-κB–associated inflammatory genes, including LTB, TNF, CCR6, and IL6." (PMID 39225100, 2024). "We noticed that, within CD45 RA–CCR7+ central memory Tregs, the frequency of CCR4+ CCR6+ CXCR3– Th17-like Tregs decreased in patients with sarcoidosis compared to the control group (26.65% (21.98; 32.04) vs. 32.59% (25.73; 38.39) with p < 0.01)." (PMID 37189479, 2023). "Next, we found increased levels of CXCR3-expressing Th1-like and Th17.1-like Treg cells in peripheral blood samples from patients with sarcoidosis, while CCR6-expressing Th17-like Tregs decreased." (PMID 37189479, 2023). "CXCR3-expressing Treg cell subsets—Th1-like CCR60078CXCR3+ Tregs and Th17.1-like CCR6+ CXCR3+ Tregs—significantly increased in patients with sarcoidosis vs. the control group (14.4% vs. 10.5% with p < 0.01 and 27.9% vs. 22.8% with p < 0.01, respectively)." (PMID 37189479, 2023). "In blood, we observed Th17.0 (CCR6+CCR4+CXCR3−) cells with increased frequencies in sarcoidosis compared to health." (PMID 32774332, 2020). "We also noted a statistically significant increase in central memory CXCR5+CCR6–CXCR3– follicular Th cells, as wells as effector memory CXCR5+CCR6–CXCR3– and CXCR5+CCR6+CXCR3– follicular Th cells in both groups of patients with sarcoidosis vs. healthy controls." (PMID 41376646, 2025). "In contrast, activated macrophages like in active sarcoidosis are highly CCR6-positive." (PMID 38334630, 2024). "Sarcoidosis-associated ILC1s also expressed CCL20, which may signal to T helper and B cells through CCR6." (PMID 39225100, 2024). "To test this, we used flow cytometry to compare the T-bet-expressing frequencies in peripheral blood Th17.0 (RORγt+CCR6+CCR4+CXCR3−) cells between sarcoidosis subjects with different clinical trajectories defined by longitudinal changes in lung function and immunosuppression use." (PMID 32774332, 2020). "In contrast, additional phenotyping of CD4+CD45RA- memory T cells demonstrated an expansion of CXCR5-expressing T follicular helper (TFH)-like cells with a significant increase of CXCR3-expressing TFH1-like cells and a decrease of CCR6-expressing TFH17-like cells when compared to sarcoidosis." (PMID 33613543, 2020). "For example, a simultaneously increased BAL fluid level of CCL18 and TGF-β1 secreting CCR6+ CD4+ T-cells would raise clinical suspicion of fibrosing sarcoidosis, and the clinician could consider prescribing anti-fibrotic agents to minimize the damage of future fibrotic scarring." (PMID 33036432, 2020). "It is worth mentioning that in the BALF derived from patients with sarcoidosis, an increase of ligands for CXCR3 and CCR6 (e.g., CXCL10 and CCL20, respectively) is seen." (PMID 41376646, 2025). "A significant increase was demonstrated in CCR6+ Th17.1 cells, which produced a large amount of IFN-γ in both BAL fluid and mediastinal lymph nodes in patients with sarcoidosis vs. healthy controls." (PMID 37189479, 2023). "In contrast, in bronchoalveolar lavage (BAL), we observed “Th17.1” (CCR6+CCR4−CXCR3+) cells, with increased frequencies in sarcoidosis compared to health." (PMID 32774332, 2020). "CXCR3− CCR6− Tfh2 and CXCR3− CCR6+ Tfh17 cells increased, while CXCR3+ CCR6− Tfh1 and CXCR3+ CCR6+ CCR4− Tfh17.1-like cells decreased in sarcoidosis patients." (PMID 33036432, 2020).
sarcoidosis (continued). "Furthermore, we found that Treg cells had a ‘proinflammatory’ phenotype, since CXCR3-expressing Treg cell subsets, including CCR6-CXCR3+ Th1-like and CCR6 + CXCR3+ Th17.1-like Treg cells, were elevated in peripheral blood samples from patients with sarcoidosis compared to healthy controls." (PMID 39598118, 2024). "Thus, we speculate that the interaction of CCR6 and CCL18 might be pivotal for the progress of IPF, whereas in fibrosis, due to sarcoidosis or HP, these processes are obviously driven by other factors." (PMID 38334630, 2024).
viral infection (9 papers, 2013 to 2023). "After viral infections, immature LCs are recruited to the epidermis via chemokine (C-C-motif) receptor 6 (CCR6), which is the receptor for chemokine (c-c-motif) ligand 20 (CCL20) increasingly expressed by infected cervical keratinocytes." (PMID 36311788, 2022). "Role of CCR6 was further clarified when ligands to CCR6 was reported to inhibit the viral infection." (PMID 24009735, 2013). "We detected proviral DNA as alternative evidence in establishing viral infection using CCR6-coreceptor." (PMID 24009735, 2013). "CCR6 is induced by virus infection and modulates the migration of immune cells." (PMID 32986779, 2020). "However, CCR6 might be important window for viral infection when alternative coreceptors are blocked or down regulated, as described for alternative coreceptors in CCR5-null situation." (PMID 24009735, 2013). "The expression of CCR6 influences migration of memory CD4+ T-cell subsets into the intestine, brain, and other tissues, and may contribute disseminating viral infection." (PMID 24009735, 2013).
Allergy (8 papers, 2011 to 2025). An allergy is an immune response or reaction to substances that are usually not harmful. "In line with previous allergy models in the eye and lungs, CCR6-deficiency impaired total IgE responses upon intraperitoneal NP-KLH/Alum immunization." (PMID 35812408, 2022). "We further explored the relationship between the level of CD4+CCR6+CRTh2+ memory Th2 cells and history of allergic diseases such as AR and AD." (PMID 34090369, 2021). "Some studies have suggested that CCL20/CCR6 interactions are important in the development of Th2 responses and allergy." (PMID 27014260, 2016). "T-cell transfer studies demonstrated that CCR6/CD196 was required to manifest allergic disease in the gastrointestinal tract." (PMID 21991511, 2011). "The expression of Ccl8, known to attract actors of allergy and inflammation, was elevated in both Spink5-/- and Spink5-/-Klk5-/- skin, whereas Ccl20, a chemoattractant for CCR6+ cells including dendritic cells and Th17 cells, showed a significant increase only in Spink5-/- skin." (PMID 26390218, 2015). "IL‐9 producing TH9 cells (CCR4− CCR6+ CCR10− CXCR3+) can be induced by the growth factor TGF‐β and IL‐4 from TH2 cells and are similarly involved in immunity against intestinal helminths and onset of allergies." (PMID 36740883, 2023). "TH2 cells (CCR4+ CCR6− CCR10− CXCR3−) orchestrate defense against large extracellular pathogens and helminths by secretion of IL‐4, but are also involved in inflammatory disorders, such as asthma and allergies." (PMID 36740883, 2023).
gastric cancer (8 papers, 2014 to 2025). A primary or metastatic malignant neoplasm involving the stomach. "The expression of CCR6 and CrkL is also significantly associated with metastasis, stage, and poor prognosis of gastric cancer." (PMID 32707869, 2020). "CCL20/CCR6 induced gastric cancer EMT through the activation of the AKT pathway in response to CrkL; similar results were found with CCL21/CCR7 axis activated JAK2/STAT3 signaling pathways in promoting stemness of OSCC EMT progression." (PMID 34943853, 2021). "CT10 regulator of kinase like protein (CrkL) has been identified as a key regulator in EMT, and both CCR6 and CrkL are aberrantly expressed in gastric cancer specimens." (PMID 32707869, 2020). "Upregulated CCR6 protein expression has also been observed in the gastric cancer tissues." (PMID 32707869, 2020). "On the other hand, CrkL played a crucial role in mediating the EMT induced by the CCL20/CCR6 axis through the Akt signaling pathway, rather than the Erk1/2 pathway during gastric cancer development." (PMID 40362257, 2025). "Evidence was accumulated that chemokines and their receptors had a strong relationship with poor clinical outcomes in different tumor progression, such as that CCR6 and CXCL16/CXCR6 were involved in regulation proliferation, metastasis, and EMT in ESCC and Gastric cancer tumorigenesis." (PMID 34943853, 2021).
malaria (8 papers, 2015 to 2023). Malaria is a serious and sometimes fatal disease caused by a parasite that commonly infects a certain type of mosquito which feeds on humans. "Therefore, our data propose that the prolonged survival of CCR6 KO mice after PbNK65 malaria is associated with a decreased serum IL-12 p70 production." (PMID 35730803, 2022). "Consistent with the emergence of Tr1 cells from Th1 subsets, the majority of Tr1 cells where Th1-like (CXCR3+/CCR6-/CXCR5-/FoxP3-) at day 0 during malaria (median 65.4%, IQR 62.5-73.8%)." (PMID 37968278, 2023). "If CCR6 KO mice present a diminished frequency of these cell subsets and an ensuing milder malaria than WT mice, it needs to be confirmed." (PMID 35730803, 2022). "In conclusion - We found evidence that the CCR6 expression can influence the survival against the PbNK65 liver- and blood-stage malaria in C57Bl/6 mice." (PMID 35730803, 2022). "To ensure that the higher survival pattern found in CCR6 KO mice was related to the immunity against the malaria liver stage, we quantified the liver parasitic loads in the challenged mice through qPCR." (PMID 35730803, 2022). "Frequencies of CXCR3+CCR6− TFH1s increase transiently but significantly during acute malaria, while CXCR3−CCR6− TFH2 frequencies decrease long-term in response to multiple malaria parasite exposures." (PMID 31156642, 2019). "Based on our previous data, we hypothesized that the enhanced malaria survival detected in CCR6 KO mice could be related to lower secretion levels of pro-inflammatory cytokines after the parasite exposure." (PMID 35730803, 2022). "CCR6 expression diminishes malaria survival in PbNK65 sporozoite-infected mice - To address the impact of the CCR6 expression in the immunity against PbNK65 malaria, our first approach was to challenge WT and CCR6 KO mice with different sporozoite numbers via iv injection." (PMID 35730803, 2022). "Since CXCR3 and CCR6 are tissue homing receptors, especially for the liver, these cells may have been directed to the liver considering the liver-tropism of malaria SPZ." (PMID 35062785, 2022). "To determine whether such flexibility was altered during malaria we evaluated the expression of CXCR3 and CC chemokine receptor 6 (CCR6) by CD4+ T cell populations in P. vivax-infected patients BT and AT." (PMID 28700710, 2017). "CCR6 KO mice have a reduced IL-12 p70 secretion in the serum upon the PbNK65-iRBC challenge in comparison to WT mice - Pro-inflammatory cytokines, such as IL-12 p70 and IFN-γ, have been described as harmful factors for the malaria resistance induced by PbNK65-iRBCs in mice." (PMID 35730803, 2022).
Obesity (8 papers, 2016 to 2025). Accumulation of substantial excess body fat. "One of the genes modulated in epidermal γδ T cells during obesity and type 2 diabetes is CCR6, which is the receptor for CCL20." (PMID 40073267, 2025). "Obesity increases the number of epidermal γδ T cells expressing CCR6 and IL-17A during wound healing, which underscores the significant impact of obesity on skewing toward an IL-17 proinflammatory response." (PMID 40073267, 2025). "Here the authors show in mouse models that obesity-induced interleukin-6 alters macrophage function to enhance CCL-20/CCR-6-mediated recruitment of B cells and γδ T cells, thereby promoting gut inflammation and CAC progression." (PMID 29695802, 2018). "For this study we chose the time point in which we observed the most CCR6+ epidermal γδ T cells in lean mice, but obesity may alter that time point." (PMID 40073267, 2025). "During the progression of MASLD, mature adipocytes release chemokines, such as CCL20, and other soluble mediators, stimulating lymphocyte migration in adipose tissue through CCR6, resulting in obesity-related inflammation, such as insulin resistance, and the occurrence of MASLD." (PMID 38550602, 2024). "Thus, epidermal γδ T cells may exhibit unique regulation and function of CCR6, especially in obesity." (PMID 40073267, 2025). "Collectively, our study assigns obesity-induced IL-6 as a modulator of the TME in CAC via macrophage polarisation and successive lymphocyte recruitment via the CCL-20/CCR-6 axis." (PMID 29695802, 2018). "In obesity, inflammatory mediators such as IL-1β, TNF-α, and interferon gamma can elevate the CCR6 expression level." (PMID 27869712, 2016). "Furthermore, the expression of chemokine signaling molecules, including CCL24, CCR6, and CXCR3, was altered in accordance with female-specific fluctuations in VAT-Treg in obesity." (PMID 32240221, 2020).
tuberculosis (8 papers, 2016 to 2025). A chronic, recurrent infection caused by the bacterium Mycobacterium tuberculosis. "CCR6+ CD4 T cells were recently implicated in the prevention of tuberculosis-associated immune reconstitution syndrome, and their detection only in young animals aligns with better disease resolution in this group." (PMID 38771046, 2024). "We observed a decrease in the circulation of Th17.1 cells in patients with tuberculosis, while the levels of “classical” and CCR6+DP Th17 in the peripheral blood of patients significantly increased compared with the control group." (PMID 35216349, 2022). "tuberculosis clonotypes, thus suggesting a potential differentiation relationship between CCR6+DP and Th1Th17." (PMID 27553844, 2016). "Of particular interest are the literature data that more than half of IFNγ-secreting Mtb-specific Th cells have the CXCR3+CCR6+ phenotype, which once again indicates the functional importance of Th17.1 cells in the development of the immune response in tuberculosis." (PMID 35216349, 2022). "To assess the potential contribution of different ‘polarized’ CD8+ T cell subsets in tuberculosis pathogenesis, we further analyzed the peripheral blood CD8+ T cells for inflammatory subsets classified by CCR6 and CXCR3 co-expression." (PMID 37761328, 2023).
vitiligo (8 papers, 2013 to 2023). Generalized well circumscribed patches of leukoderma that are generally distributed over symmetric body locations and is due to autoimmune destruction of melanocytes. "Recent GWAS have identified SNPs in the 6q27 region associated with RA (rs3093024 and rs3093023 near CCR6) and vitiligo (rs6902119 near CCR6)." (PMID 25928629, 2015). "Autoimmunity against melanocytes is an important feature in both VKH and vitiligo and therefore prompted us to investigate the four CCR6 SNPs and one FGFR10P tagSNP as candidates in our study." (PMID 23935994, 2013). "More recently, CCR6 was shown to mediate Treg migration into the skin of vitiligo patients." (PMID 37239000, 2023). "Our prioritization pipeline revealed genes like IKZF4 and CCR6 that are already well-characterized to play a significant functional role in the development of vitiligo as evident from Harmonizome Dataset and GeneMania, thus indicating reliability and reproducibility of our prioritization process." (PMID 36008553, 2022). "However, the authors hypothesized that CCL20 may be involved in the recruitment of dual producing IL-17 and IFN-γ cells (CCR6+ Th1/17 cells and Tc1/17 cells) to vitiligo skin." (PMID 36911664, 2023). "Several studies demonstrate reduced levels of CCL5/CCR4, CCL22, CCL21, and CCR6 in vitiligo skin, which could explain the failure of circulating Tregs to localize to the skin, thus suggesting that the modulating expression of these chemokines may be potential therapeutic targets in vitiligo." (PMID 36675037, 2023). "Among them, a lot of genes have been described to be involved in vitiligo, such as CXCL9, CCR6, and IL-33." (PMID 35406685, 2022). "CCL20/CCR6 signaling recruits also Tregs to the skin and Tregs lacking CCR6 have a decreased capacity to migrate to vitiligo skin and suppress depigmentation." (PMID 36911664, 2023).
atherosclerosis (7 papers, 2014 to 2024). A disease characterized by the build-up of fatty material and calcium deposition in the arterial wall resulting in partial or complete occlusion of the arterial lumen. "Our studies are the first to identify the CCL18/CCR6 axis as a regulator of immune responses in advanced murine and human atherosclerosis." (PMID 38807599, 2024). "Our study is the first to identify a role for CCR6 in regulating B-1 cell number and IgM production in PVAT and a CCR6-dependent IgM-mediated inhibition of diet-induced atherosclerosis." (PMID 33679793, 2021). "To compare the expression levels of CCR6 in B-1 and B-2 cells, we performed flow cytometry on isolated cells from various compartments and measured the frequency of CCR6+ B-1 and B-2 cells from atherosclerosis prone chow fed ApoE−/− mice." (PMID 33679793, 2021). "In human atherosclerosis, the expression of CCR6 and CCL20 in atherosclerotic lesions in the coronary and carotid arteries has been reported." (PMID 33679793, 2021). "Murine studies demonstrate that CCR6 on monocytes is important for their recruitment to aorta to aggravate atherosclerosis." (PMID 33679793, 2021). "Chemokine receptor-6 (CCR6) mediates immune cell recruitment to inflammatory sites and has cell type-specific effects on diet-induced atherosclerosis in mice." (PMID 33679793, 2021). "CCR6 expression on circulating human B cells in subjects with a high level of atherosclerosis in their coronary arteries was lower only in the putative human B-1 cells." (PMID 33679793, 2021). "Deletion of Ccr6 decreased atherosclerosis burden in the ApoE−/− mouse, which was accompanied by lower macrophage content in plaques, suggesting that CCR6 is proatherogenic." (PMID 24741577, 2014). "Collectively, our findings implicate the CCL18/CCR6 axis in the pathogenesis of atherosclerosis." (PMID 38807599, 2024). "Surprisingly, adoptive transfer (AT) of CD43− splenic B cells into B cell-deficient μMT−/−ApoE−/− mice repopulated the PerC with B-1 and B-2 cells and reduced atherosclerosis when transferred into ApoE−/−CCR6+/+sIgM−/− mice only when those cells expressed both CCR6 and sIgM." (PMID 33679793, 2021). "Because CCR6 and CXCR4 on SWM B cells potentially play a role in mediating α-gal sensitization and α-gal sensitization has previously been associated with CAD, here we explored the relationship between CCR6/CXCR4 expression on SWM B cells and atherosclerosis." (PMID 35097011, 2021). "Moreover, reduced atherosclerosis in Ccr6−/− bone marrow chimeras fed atherosclerosis-inducing diet indicates that CCR6+ hematopoietic cells contribute to lesion development." (PMID 24741577, 2014). "CCL18/CCR6 may therefore be a candidate for intervention in atherosclerosis-related inflammation, albeit that our limited understanding of chemokine pathways relevant to human atherosclerosis, in mutual interaction, warrants further study." (PMID 38807599, 2024). "In the Treg context, CCR2, CCR4 and CCR6 have previously been shown to be up‐regulated in Tregs migrating to non‐lymphoid tissues or sites of inflammation, and this may be the primary basis of their increase in the atherosclerosis phenotype." (PMID 37927302, 2023). "However, circulating human monocytes do not express CCR6, despite CCR6 on monocytes being implicated in atherosclerosis in murine models." (PMID 33679793, 2021). "Next, we studied the ability of CCL18 to drive CCR6-mediated responses in vivo in two models of inflammation: CCL18-dependent ear swelling and the more complex mouse model of atherosclerosis." (PMID 38807599, 2024).